ADAM15 (ADAM metallopeptidase domain 15)
Description:
Active metalloproteinase with gelatinolytic and collagenolytic activity. Plays a role in the wound healing process. Mediates both heterotypic intraepithelial cell/T-cell interactions and homotypic T-cell aggregation. Inhibits beta-1 integrin-mediated cell adhesion and migration of airway smooth muscle cells. Suppresses cell motility on or towards fibronectin possibly by driving alpha-v/beta-1 integrin (ITAGV-ITGB1) cell surface expression via ERK1/2 inactivation. Cleaves E-cadherin in response to growth factor deprivation. Plays a role in glomerular cell migration. Plays a role in pathological neovascularization. May play a role in cartilage remodeling. May be proteolytically processed, during sperm epididymal maturation and the acrosome reaction. May play a role in sperm-egg binding through its disintegrin domain.
Synonyms: MDC15
Tractability: Antibody: its Gene Ontology location is reachable by antibodies, with high confidence; UniProt predicts a signal peptide or a membrane-spanning region. PROTAC: ubiquitination databases record sites on it; its protein half-life has been measured.
Target class: Metallo protease MAM clan; Metallo protease; Protease; Enzyme; Metallo protease M12B subfamily
Gene: Protein-coding gene on chromosome 1 (155,050,566 to 155,062,780, forward strand). Ensembl gene ENSG00000143537.
Subcellular location: Endomembrane system; Cell junction, adherens junction; Cell projection, cilium, flagellum; Cytoplasmic vesicle, secretory vesicle, acrosome
Subcellular location (Human Protein Atlas): Vesicles
Pathways (Reactome):
Extracellular matrix organization: Degradation of the extracellular matrix; Invadopodia formation
Gene Ontology:
Molecular function: immunoglobulin receptor binding; integrin binding; metallopeptidase activity; protein binding; SH3 domain binding; metalloendopeptidase activity
Biological process: apoptotic process; cellular response to phorbol 13-acetate 12-myristate; immune response to tumor cell; innate immune response; integrin-mediated signaling pathway; negative regulation of cell growth; negative regulation of cell migration; negative regulation of cell-matrix adhesion; cell-matrix adhesion; extracellular matrix disassembly; proteolysis; male gonad development; response to hypobaric hypoxia; tissue regeneration
Cellular component: cell surface; extracellular exosome; plasma membrane; acrosomal vesicle; adherens junction; endomembrane system; motile cilium
Genetic constraint (gnomAD): Loss-of-function variants: 77 observed, 112.7 expected, observed/expected ratio (o/e) 0.68, 90% interval 0.57 to 0.83. The upper end of that interval is the gene's LOEUF score, 0.83, which puts it in group 3 of 6, group 1 being the genes least tolerant of losing a copy. Missense variants: 963 observed, 1,103.3 expected, observed/expected ratio (o/e) 0.87, 90% interval 0.83 to 0.92. Synonymous variants: 388 observed, 448.34 expected, observed/expected ratio (o/e) 0.87, 90% interval 0.8 to 0.94.
Homologues: Orthologues: chimpanzee ADAM15 (99% identical), macaque ADAM15 (96% identical), pig ADAM15 (84% identical), guinea pig ADAM15 (83% identical), dog ADAM15 (82% identical), rabbit ADAM15 (82% identical), rat Adam15 (82% identical), mouse Adam15 (80% identical), tropical clawed frog adam15 (41% identical), zebrafish adam15 (41% identical). Paralogues in human: ADAM12 (35% identical), ADAM19 (35% identical), ADAM33 (35% identical), ADAM8 (30% identical), ADAM9 (30% identical), ADAM28 (26% identical), ADAM22 (25% identical), ADAM11 (25% identical), ADAM23 (24% identical), ADAM20 (23% identical), ADAM21 (23% identical), ADAM7 (22% identical), and 8 more.
Diseases named in the same sentence as ADAM15 in open-access papers:
ADAM15 is named in the same sentence as 78 diseases in open-access papers, as found by Europe PMC text mining. Sharing a sentence is not in itself a finding about the gene and the disease. The quoted sentences say what the papers report.
breast carcinoma (20 papers, 2010 to 2025). "The ADAM15 variants were expressed in a differential manner in breast carcinoma tissues in comparison with normal tissues." (PMID 38317965, 2024). "It was reported in the literature that the ectodomain shedding of E-cad by ADAM-15 supports the ErbB receptor activation associated with the progression of prostate and breast cancer." (PMID 37446087, 2023). "In breast cancer, particular ADAM15 variants that result from alternative splicing of exons encoding the ICD have different functional consequences in relation to patient outcomes and shedding of FGFR2iiib5,12." (PMID 31467400, 2019). "We previously cloned and characterised alternatively spliced variants of ADAM15 that differ in their intracellular domains and demonstrated correlation of the expression of specific variants with breast cancer prognosis." (PMID 31467400, 2019). "ADAM15 cytoplasmic domain variants have been implicated in mammary carcinoma, while an ADAM12 secreted isoform promotes breast tumor metastasis in vivo." (PMID 24375628, 2014). "The ADAM15 protein is known to display tumor suppressive activities when it is released as an exosomal component, and abnormal expression and dysregulation of alternative splicing in ADAM15 has been previously associated with breast cancer." (PMID 32064050, 2020). "Interestingly, aberrant patterns of ADAM15 splice variants have been observed in human breast cancer cells." (PMID 24116070, 2013). "Another ADAM associated with outcome in patients with breast cancer is ADAM15." (PMID 21906355, 2011). "Certain ADAM-15 variants have been associated with poor survival of breast cancer patients." (PMID 22069559, 2010). "As one of the catalytically active ADAMs, ADAM15 has been reported to be overexpressed in various malignancies, including breast cancer, prostate cancer and lung cancer." (PMID 34426560, 2021). "Some studies have demonstrated that ADAM15 is overexpressed in many tumors, such as prostate cancer, melanoma and breast cancer." (PMID 34426560, 2021). "Upregulation of ADAM15 expression in breast cancer and prostate cancer has been related to tumor aggressiveness and metastasis." (PMID 34426560, 2021). "To confirm this further we made use of T47D breast cancer cells that have high expression levels of endogenous ADAM15 isoforms A, C and E, as well as of Claudin-1." (PMID 31467400, 2019). "Moreover, the investigation also revealed ADAM15 variant-specific and catalytic activity-dependent upregulation of the expression of the tight junction protein Claudin-1, which may help to explain some aspects of the actions of ADAM15 in breast cancer." (PMID 31467400, 2019). "In summary, our data show that ADAM15 expression in breast cancer cells leads to upregulated expression of the tight junction protein Claudin-1, which involves activation of the PI3K/mTOR pathway." (PMID 31467400, 2019). "How individual ADAM15 isoforms contribute to contrasting breast cancer prognosis has been unclear so far." (PMID 31467400, 2019). "Immunofluorescence analysis of endogenous Claudin-1 and ADAM15 in T47D breast cancer cells also demonstrated Claudin-1 and ADAM15 co-localisation at cell-cell junctions and the cell periphery." (PMID 31467400, 2019). "To elucidate the role of ADAM15 isoforms in breast cancer progression, we generated an isogenic cell panel expressing each ADAM15 isoform in MDA-MB-231 cells." (PMID 31467400, 2019). "Previously we have shown that differential expression of ADAM15 spliced isoforms has prognostic significance in breast cancer patients." (PMID 31467400, 2019). "For example, ADAM15 is overexpressed in bladder, prostate and breast cancers and its substrate include EGFR ligands and TGF-β that are related to cancer cell proliferation." (PMID 29423060, 2018). "ADAM15 catalyzes and sheds soluble E-cadherin, which binding to the ErbB receptor in breast cancer cells." (PMID 28145888, 2017).
breast carcinoma (continued). "ADAM15 is a multi-domain disintegrin metalloproteinase that is upregulated in several solid malignancies including prostate and breast cancer and elevated expression of ADAM15 has also been correlated with the metastatic progression of these tumors." (PMID 26930657, 2016). "One of the catalytically active ADAMs, ADAM15, has been reported to be overexpressed in numerous malignancies including melanoma, prostate cancer and breast cancer." (PMID 26930657, 2016). "In examining disease progression tumor arrays of prostate and breast cancer, we found a significant correlation between elevated ADAM15 levels and angio-invasive breast cancer." (PMID 26930657, 2016). "ADAM-15 expression is increased in breast cancer, where its overexpression is coincidental with Her2/neu and a more aggressive and invasive phenotype." (PMID 24317528, 2013). "Increased ADAM-15 mRNA and protein has been noted in lung, prostate, and breast cancer, and overexpression in breast cancer is coincidental with Her2/neu expression and a more aggressive and invasive phenotype." (PMID 24317528, 2013). "The proposed role of miR-98 in decreasing MMP11 and ADAM-15 expression can explain the tumorigenic properties of breast cancer cells." (PMID 23211491, 2012). "Using breast cancer cell lines, the same authors reported that ADAM-15 cleaved cadherin E after growth factor deprivation." (PMID 22069559, 2010). "It was reported that mRNA and/or protein levels of ADAM-15 are upregulated in multiple adenocarcinomas including cancer of the breast, stomach, lung, pancreas and prostate." (PMID 22069559, 2010). "It is tempting to speculate that ADAM15 mediated Claudin-1 upregulation might have a role in defining the metastatic niche, enhancing breast cancer cell attachment to hepatocytes and metastasis to the liver." (PMID 31467400, 2019). "Of particular importance, the ADAM-15-mediated cleavage and release of sE-cad stimulates the Human epidermal growth factor receptor 2 (Her2/neu), a transmembrane protein overexpressed in 20%–25% of breast cancer patients." (PMID 24317528, 2013). "In combination with Herceptin, small molecules capable of targeted downregulation of ADAM-15 expression, such as those stabilizing the promoter G4, have the potential for synergism and a marked improvement on the lives of thousands of breast cancer patients a year." (PMID 24317528, 2013). "ADAM-15 is implicated in EGFR ligand shedding, possibly through EGFR transactivation and catalyzes the shedding of a soluble E-cadherin fragment that is increased during the progression of breast cancer." (PMID 21197111, 2010). "Moreover, 4 isoforms of ADAM15 were examined in mammary carcinoma tissues." (PMID 38317965, 2024). "We show for the first time ADAM15 isoform-, and catalytic function-dependent upregulation of Claudin-1 expression, which may be responsible for the effects of ADAM15 on cancer cell phenotypes and prognostic outcomes for breast cancer patients." (PMID 31467400, 2019). "Introduction of shRNA targeting the 3′UTR of ADAM15 into T47D cells down-regulated endogenous ADAM15 expression, leading to a concomitant decrease in Claudin-1 levels confirming that ADAM15 is responsible for driving Claudin-1 expression in these breast cancer cells." (PMID 31467400, 2019). "Several reports have shown that members of the ADAM family are overexpressed in human cancers such as ADAM8 in human renal cell carcinomas, ADAM15 in lung carcinoma, and ADAM17 in breast cancers." (PMID 34249950, 2021). "ADAM-15 and HER2/neu were shown to be correspondingly upregulated in breast cancer in seven independent microarray studies." (PMID 24317528, 2013). "Gain of 1q in cancer, specifically in breast cancer has previously been described but is impressively evidenced in this study by frequent co-amplification of the SYK-regulated SPRR1A, SPRR1B, MUC1, RAB25, and ADAM15, genes located within chromosome 1q." (PMID 24523870, 2014).
breast carcinoma (continued). "For instance, ADAM15 catalytic activity was required for claudin-1-dependent regulation of growth and mobility of breast cancer cells, but was not required for its role in promoting pathological neovascularization in a mouse model of oxygen-induced retinopathy." (PMID 37388246, 2023). "Targeted downregulation of both ADAM-15 and HER2/neu function synergistically kills breast cancer cells, but to date there are no therapeutic options for decreasing ADAM-15 function or expression." (PMID 24317528, 2013).
prostate carcinoma (10 papers, 2005 to 2025). A carcinoma that arises from epithelial cells of the prostate gland. "We had previously reported that the expression of ADAM15 was associated with the metastatic progression of breast and prostate cancers." (PMID 26930657, 2016). "The authors confirmed that ADAM15 mRNA and protein levels were elevated in prostate cancer cells, and its expression was found to be significantly higher during metastatic progression." (PMID 40725774, 2025). "ADAM15 is expressed in several solid malignant tumors, such as breast cancer and prostate cancer, and is involved in the progression to metastatic disease." (PMID 30634456, 2019). "ADAM15 expression is reported in several solid malignant tumors, such as breast and prostate cancers." (PMID 30634456, 2019). "We have previously demonstrated that siRNA targeting of ADAM15 in prostate cancer cells not only reduced tumor cell migration and invasion, it also altered the tumor cell adhesion profile and completely inhibited the overt metastasis of these cells in vivo." (PMID 26930657, 2016). "We have shown that the inhibition of ADAM15 expression in PC-3 prostate cancer cells reduced tumor growth and prevented metastasis." (PMID 26930657, 2016). "The level of overexpression of ADAM15 in breast and prostate cancer has been correlated with tumor aggressiveness and metastatic progression." (PMID 26930657, 2016). "ADAM15 mRNA and protein levels are increased in prostate cancer and its expression is significantly increased during metastatic progression." (PMID 25693204, 2015). "In another study, knockdown of ADAM15 decreased malignant properties of prostate cancer PC-3 cells, such as migration and adhesion." (PMID 24495306, 2014). "Finally, the transmembrane glycoprotein, ADAM15, might also be targeted by miR-1247, to facilitate prostate cancer metastasis." (PMID 21698188, 2011). "Overexpression of ADAM species is known in tumor cell lines, for example, ADAM10, ADAM12 and ADAM15 in hematological malignant tumor cell lines, and ADAM9, ADAM10, ADAM15 and ADAM17 in prostate cancer cell lines." (PMID 16277668, 2005).
rheumatoid arthritis (9 papers, 2018 to 2025). A chronic, systemic autoimmune disorder characterized by inflammation in the synovial membranes and articular surfaces. "ADAM15 is involved in the response to hypoxia, proteolytic ectodomain processing of cytokines, cell adhesion signaling, and angiogenesis in endothelial cells, and it is associated with atherosclerosis, rheumatoid arthritis, intestinal inflammation, and inherent angiogenesis." (PMID 35668171, 2022). "For example, ADAM-15 was found to be a mediator of rheumatoid arthritis and intestinal inflammation as well as inherent angiogenesis." (PMID 36172139, 2022). "Fibroblast-derived ADAM15 promotes an anti-apoptotic phenotype in fibroblasts in the joints of patients with rheumatoid arthritis by activating the Src/focal adhesion kinase pathway." (PMID 32677970, 2020). "So far, most functions of ADAM15 in intestinal bowel disease, cardiac disease, atherosclerosis, rheumatoid arthritis, lung diseases, angiogenesis, and cancer formation have been attributed to its plasma membrane-resident form in adherent cells of different origins." (PMID 41340056, 2025). "ADAM15 is expressed by monocyte/macrophage-like and lymphocyte cell lines in vitro, macrophages activated in vitro, and macrophages and fibroblasts in the joints of patients with rheumatoid arthritis." (PMID 32677970, 2020). "Soluble forms of ADAM15 (sADAM15) have been detected in serum and synovial fluid samples from patients with rheumatoid arthritis, and may be generated via proteolytic shedding of ADAM15 from cell surfaces." (PMID 32677970, 2020). "Single-nucleotide polymorphisms in the ADAM15 locus are linked to rheumatoid arthritis, but have not linked to COPD." (PMID 32677970, 2020). "In addition to the roles played by ADAM15 in atherosclerosis and pathological angiogenesis, accumulating evidence indicates that ADAM15 might be involved in other inflammatory disorders, such as rheumatoid arthritis (RA) and inflammatory bowel disease (IBD)." (PMID 41039222, 2025). "Here, we describe a mechanotransduction pathway in rheumatoid arthritis synovial fibroblasts (RASF), which is critically dependent on the disintegrin metalloproteinase ADAM15 and N-cadherin (NCAD)." (PMID 40118917, 2025). "In this study, we investigated the role of ADAM15 in rheumatoid arthritis (RA) angiogenesis." (PMID 30634456, 2019). "ADAM15 is known to be expressed by activated macrophages in other diseases, but ADAM15 was previously reported not to be expressed by CD8+ T cells either in healthy subjects or patients with rheumatoid arthritis." (PMID 32677970, 2020). "It is highly upregulated in the inflamed synovial membrane of patients with osteoarthritis (OA) and rheumatoid arthritis (RA) and an accelerated development of murine osteoarthritis in ADAM15 knockout mice suggested a homeostatic rather than a destructive role of ADAM15 in cartilage remodeling." (PMID 30265671, 2018).
atherosclerosis (6 papers, 2010 to 2025). A disease characterized by the build-up of fatty material and calcium deposition in the arterial wall resulting in partial or complete occlusion of the arterial lumen. "Altered ADAM15 expression has been associated with various human diseases, including cancers, cardiovascular disease, atherosclerosis, and arthritis." (PMID 41039222, 2025). "ADAM15 is abundantly expressed in vascular cells, including endothelial and smooth muscle cells (SMCs), and is implicated in vascular pathologies, including atherosclerosis and pathological angiogenesis." (PMID 41039222, 2025). "There is growing evidence of links between ADAM-15 and human diseases including cancer and atherosclerosis." (PMID 22069559, 2010). "ADAM-15 interacts with αVβ3 and α5β1 integrins, both of which are involved in endothelial cell migration indicating a possible role in atherosclerosis." (PMID 22069559, 2010). "Furthermore, it has been shown that the binding of platelet αIIbβ3 integrin to endothelial ADAM15 results in activation and recruitment of additional platelets, which leads to thrombus formation, underscoring the role of ADAM15 in atherosclerosis." (PMID 41039222, 2025). "ADAM15, together with its binding partners, integrins α5β1 and αVβ3, have been found to be upregulated in atherosclerotic arterial areas in comparison with normal samples, which points to their collective involvement in atherosclerosis." (PMID 41039222, 2025). "The ADAM15-stimulated migration of endothelial cells and SMCs may contribute to angiogenesis, to tissue remodeling, and to plaque formation in atherosclerosis." (PMID 41039222, 2025). "Furthermore, it has been shown that the binding of platelet αIIbβ3 integrin to endothelial ADAM15 results in the activation and recruitment of additional platelets, which leads to thrombus formation, underscoring the role of ADAM15 in atherosclerosis." (PMID 41039222, 2025).
colon carcinoma (6 papers, 2018 to 2025). "The authors observed decreased expression of ADAM15 in CRC associated with a loss of differentiation in a subset of colon carcinomas, which indicates that the role of ADAM15 in cancer progression is tissue-specific." (PMID 35565436, 2022). "Some investigators assessed ADAM15 expression in colon carcinomas using both IHC and mRNA quantitative methods." (PMID 40725774, 2025). "However, data from colon cancer studies have shown that ADAM15 overexpression inhibits metastasis formation, suggesting different roles for ADAM15 in other tissues." (PMID 41340056, 2025).